TNF (tumor necrosis factor)
Diseases named in the same sentence as TNF in open-access papers (continued):
Sharing a sentence is not in itself a finding about the gene and the disease.
sarcopenia (continued). "A key role for inflammation as a driver of muscle wasting has been suggested by a small study which showed sarcopenia was reduced by anti-TNFα monoclonal antibody therapy." (PMID 34895316, 2021). "The search for common genetic factors for sarcopenia and IBD also revealed IL6, IL10, and TNF, as well as LTA, which encodes a multifunctional cytokine primarily involved in the immune functions." (PMID 34680417, 2021). "Specifically, IL-6 and TNF-α high concentrations have been directly related to the process of sarcopenia and frailty in both humans and rats." (PMID 34336096, 2021). "Secondly, increased levels of pro-inflammatory factors interleukin-6 (IL-6) and tumor necrosis factor-α (TNF-α) are reported in patients with sarcopenia and Alzheimer's cognitive impairment." (PMID 33714959, 2021). "The antioxidant transcription factor Nrf2 has been shown to be downregulated with mechanical unloading, while providing protection against muscle wasting and oxidative stress with hibernation, sarcopenia, and TNF-alpha-induced atrophy." (PMID 33806917, 2021). "This is consistent with previous findings, and it seems that increased IL-10 concentration induced by exercise continuously inhibited inflammatory factors, such as TNF-α, in older adults with sarcopenia and OA with high inflammatory markers." (PMID 34200794, 2021). "Inflammatory markers including interleukin 6 (IL-6), C Reactive Protein (CRP) and tumor necrosis factor-alpha (TNF-a) were shown to positively correlate with sarcopenia." (PMID 33902634, 2021). "Research has shown that, with treatments such as anti-TNF agents, sarcopenia and disease activity can be reversed." (PMID 33671473, 2021). "On the other hand, increased levels of the tumor necrosis factor can stimulate catabolic pathways in skeletal muscles, eventually leading to sarcopenia." (PMID 34946459, 2021). "TNF-α is a cytokine involved in systemic inflammation and a significant determinant of sarcopenia in patients with stable COPD." (PMID 35069243, 2021). "Chronic low-grade inflammation is characterized by an increase in circulating concentrations of tumor necrosis factor α (TNF-α), interleukin 6 (IL-6), IL-1 β, etc., and is present in numerous chronic diseases, including sarcopenia." (PMID 34948558, 2021). "Sarcopenia has been related to nuclear factor κB and protein kinase B signaling through secretion of tumor necrosis factor-α, transforming growth factor-β and interleukin-6." (PMID 34835985, 2021). "Increased levels of IL-6 and TNF-α and a reduced level of IL-10 have been reported in cases of sarcopenia." (PMID 34371826, 2021). "It has been reported that inflammatory markers such as TNF-α and IL-6 play a key role in the occurrence of sarcopenia and these inflammatory markers are also related to depressive symptoms." (PMID 33424964, 2020). "The clinical data from a large population indicate that elderly sarcopenia patients have significantly elevated concentrations of proinflammatory cytokines such as IL-6 (Interleukin 6) and TNF-α (Tumour Necrosis Factor-Alpha) 8-10." (PMID 32226296, 2020). "TNFα derived from myeloid cells and TNFα intrinsic to muscle both appear to contribute to age-related sarcopenia." (PMID 33291708, 2020). "Tumor necrosis factor-alpha, C-reactive protein, and interleukin-6 have been correlated with a decline in muscle mass and strength, suggesting a direct involvement in sarcopenia pathogenesis." (PMID 31947528, 2020). "Many inflammatory markers, such as interleukin- 6 (IL-6), C-reactive protein (CRP), and tumor necrosis factor α (TNF-α), have been linked with sarcopenia." (PMID 33160322, 2020). "Genetic ablation of TNFα, which is mainly expressed by myeloid cells in skeletal muscle, reduces sarcopenia and improves satellite cell activation in aged mice." (PMID 33260150, 2020). "Considering cytokines as targets for therapeutic strategies in sarcopenia, certain treatments have been developed that act upon the TNF-α signaling pathways." (PMID 33266508, 2020).
sarcopenia (continued). "Sarcopenia and loss of muscle strength have been associated with increased serum concentrations of inflammatory markers, including IL-6, CRP, and TNF-alpha." (PMID 31590379, 2019). "Patients with sarcopenia had lower BMI, higher TNF-alpha, lower hand-grip strength, SMI and gait speed." (PMID 31540409, 2019). "Previous study have suggested that infliximab, a TNF-α inhibitor, can suppress NF-κB activation and reverse the condition of inflammatory mediated sarcopenia in patients with Crohn’s disease." (PMID 31660942, 2019). "Studies have reported increased levels of circulating pro-inflammatory cytokines such as IL-6 and TNFα in elderly sarcopenia cases." (PMID 30541467, 2018). "The primary, novel finding of the present investigation is that TNF‐α expression in normal, healthy, aging animals plays a significant role in influencing sarcopenia and satellite cell numbers." (PMID 30256507, 2018). "Some studies have suggested a relationship between inflammatory cytokines (such as IL-6 and TNFα) and sarcopenia in humans." (PMID 29351340, 2018). "Twenty‐month‐old TNF‐α‐null mice that received wild‐type BMT showed a partial restoration of sarcopenia." (PMID 30256507, 2018). "We found that systemic ablation of tumor necrosis factor‐α (TNF‐α) prevented sarcopenia and prevented age‐related change in muscle fiber phenotype." (PMID 30256507, 2018). "Future investigations are needed to fully elaborate the mechanism through which TNF‐α contributes to muscle aging and the translational potential of reducing sarcopenia through TNF‐α‐related therapies." (PMID 30256507, 2018). "Collectively, we show that myeloid cell‐derived TNF‐α contributes to muscle aging by affecting sarcopenia and muscle cell fusion with aging muscle fibers." (PMID 30256507, 2018). "We found that ablating TNF‐α resulted in reduced sarcopenia and produced hypernucleation of aging myofibers." (PMID 30256507, 2018). "Others have observed elevated levels of circulating pro-inflammatory markers such as IL-6 and TNFα in elderly sarcopenia cases." (PMID 30541467, 2018). "The purpose of this study is to investigate the relationship between changes in body composition and the incidence of sarcopenia vs. inflammatory factors interleukin-6 (IL-6) and tumor necrosis factor-α (TNF-α)." (PMID 28701179, 2017). "Our research results indicated that IL-6 and TNF-α serum levels in elderly subjects with sarcopenia were higher than levels in the control group, and BMI VFA were independent risk factors for inflammatory cytokines IL-6 by multiple regression analysis." (PMID 28701179, 2017). "Further research is clearly indicated to determine the exact role of TNF in the sarcopenia of inflammatory arthritis." (PMID 28740214, 2017). "The emergence of sarcopenia was accompanied by increased levels of inflammation factors TNF-α and IL-6." (PMID 28701179, 2017). "IL-6 and TNF-α levels in the Sarcopenia group were higher than the control group; the comparison between groups showed significant difference (P < 0.05)." (PMID 28701179, 2017). "Recent findings suggest that some inflammatory cytokines including TNF-α and IL-6 are involved in pathophysiology of age-related sarcopenia." (PMID 29259690, 2016). "This specific restriction in the expression of TNFα clearly indicates that this population of cells should further be studied as they may represent attractive targets in the treatment of T2D and potentially as well other conditions associated with aging such as sarcopenia." (PMID 25337938, 2014). "Inflammation, which generally increases with age, is a key factor contributing to sarcopenia, and high level of TNF-α is partly responsible for the decrease in muscle protein synthesis that occurs in the elderly." (PMID 22536489, 2012). "Specifically, we will highlight the importance of cytokines, such as tumor necrosis factor α (TNFα), as a mediator of muscle wasting and as a therapeutic target for the treatment of both sarcopenia and cachexia." (PMID 21832306, 2011).
sarcopenia (continued). "Several studies have implicated elevated levels of two cytokines, interleukin-6 (IL-6) and TNFα, in the development of sarcopenia." (PMID 21832306, 2011). "Several apoptotic pathways are operative in aged muscles, with the mitochondria- and TNF-α-mediated pathways likely being the most relevant to sarcopenia." (PMID 20191247, 2010). "Objective radiological assessment of sarcopenia may contribute here, while serum metabolomic markers, TNF‐alpha, IL‐6 and neutrophil–lymphocyte ratio may have a role." (PMID 40781491, 2026). "These cytokines, viz., IL-6, TNF-α, and IL-1β, activate muscle-specific protein degradation pathways through E3 ubiquitin ligases TRIM63 and FBXO32, linking NSCLC progression to cancer-associated sarcopenia." (PMID 42278237, 2026). "The multidimensional mechanisms by which TNF‐α could mediate the restoration of muscle mass and motor function in sarcopenia were systematically explored by integrating molecular regulatory networks and functional phenotypic analysis." (PMID 41208593, 2025). "In the present study, we observed that the TNF levels were the lowest in the MSC + Ex group, indicating a synergistic effect of the combination of exercise and ADMSCs in decreasing inflammation associated with sarcopenia." (PMID 39859165, 2025). "Adipose tissue serves not only as an energy store but also as an active endocrine organ capable of releasing inflammatory cytokines, such as TNF-α and interleukin-6 (IL-6), which can contribute to muscle breakdown, inhibit muscle synthesis, induce muscle atrophy, and ultimately lead to sarcopenia." (PMID 40255379, 2025). "Blocking TNF-α signaling with pharmacological inhibitors has been shown to prevent muscle atrophy and improve survival in aging models, highlighting its central role in sarcopenia pathogenesis." (PMID 40843723, 2025). "TNF is known to play a significant role in the pathogenesis of sarcopenia." (PMID 39859165, 2025). "Previous literature has reported that the mechanism of IL-6 and TNF-α induced sarcopenia may have the following aspects." (PMID 40265008, 2025). "Additionally, TNF-α promotes muscle proteolysis and mitochondrial dysfunction, contributing to sarcopenia-related frailty." (PMID 41488632, 2025). "In patients with sarcopenia, protein supplementation, whether soy or whey protein, was also capable of decreasing serum TNF-α." (PMID 41141350, 2025). "Our findings revealed that EVs‐derived myostatin, P3NP and TNF‐α were strongly correlated with sarcopenia‐related factors, specifically muscle function and muscle performance, highlighting the potential of circulating EVs as reliable biomarkers for sarcopenia." (PMID 40162588, 2025). "Additionally, pro-inflammatory cytokines like interleukin-6 (IL-6) and tumor necrosis factor-α (TNF-α) are elevated in both sarcopenia and OSA." (PMID 40055243, 2025). "Furthermore, apelin implicated in sarcopenia and inflammatory biomarkers (CRP, TNF-α, IL-6, IL-8, and LTB4) were also measured in the serum." (PMID 40649397, 2025). "Similarly, TNF‐α levels were 0.11 ± 0.08 pg/mL in the normal group and 0.15 ± 0.17 pg/mL in the sarcopenia group (p = 0.597)." (PMID 40162588, 2025). "This study investigated the correlation of known sarcopenia biomarkers—adiponectin, myostatin, P3NP, CRP and TNF‐α—measured from plasma‐derived EVs with muscle mass, function and performance in an Osteoporosis Sarcopenia cohort at the Seoul National University Bundang Hospital." (PMID 40162588, 2025). "Additionally, therapeutic strategies targeting pro-inflammatory cytokines, particularly TNF-α, are gaining recognition as potential approaches to mitigate sarcopenia." (PMID 39852400, 2025). "The role of TNF-α in sarcopenia involves complex biological mechanisms." (PMID 40969368, 2025).
sarcopenia (continued). "Thus, Fractions 5–7 were confirmed as high‐purity EVs‐enriched fractions and subsequently used to quantify sarcopenia‐associated markers, including adiponectin, myostatin, P3NP, CRP and TNF‐α, within plasma‐derived EVs using ELISA." (PMID 40162588, 2025). "Sarcopenia may contribute to anti-TNF pharmacokinetic failure through increased clearance or reduced drug uptake, resulting in inadequate drug levels and a lack of response to therapy." (PMID 40616584, 2025). "Additionally, chronic exposure to TNF‐α established a sustained sarcopenia‐like phenotype, characterized by persistent muscle atrophy, reduced muscle fibre volumes and functional decline." (PMID 40810394, 2025). "A randomized controlled study demonstrated that modified Buzhong Yiqi Decoction combined with conventional intervention significantly reduced serum levels of IL-6 and TNF-α in elderly patients with sarcopenia after 2 months of treatment compared to conventional intervention alone (P < 0.05)." (PMID 40661078, 2025). "Furthermore, Pistilli and colleagues found increased levels of TNF-α and FAS receptor mRNA in the skeletal muscle of aged rats, suggesting its involvement in the nuclear apoptosis that occurs during age-associated sarcopenia." (PMID 40564069, 2025). "A longitudinal study found that peripheral tumor necrosis factor-α might be a marker for the progression of sarcopenia in patients with hip fractures." (PMID 41561057, 2025). "TNF-α is implicated not only in the pathogenesis of sarcopenia but also in the downregulation of CD28 expression on T cells, leading to the accumulation of CD28—T lymphocytes, a hallmark of immune aging that contributes to a vicious cycle of sarcopenia." (PMID 40852355, 2025). "This could explain the simultaneous increase in IL-6 and TNFα in patients with sarcopenia and probable sarcopenia compared with non-sarcopenia individuals." (PMID 41345186, 2025). "In one cohort studies, anti-TNF was used and sarcopenia reversion after 24 months." (PMID 38493139, 2024). "According to the authors, irisin could be used in the diagnosis of sarcopenia, thus preventing its consequences in subjects with cancer, while TNF-α appears to play a role in its pathophysiology by inhibiting protein synthesis in muscle cells." (PMID 38672282, 2024). "In sarcopenia, the major pro-inflammatory cytokines include TNF-α, IL-6, and interleukin-1 (IL-1)." (PMID 39582665, 2024). "Although the significances of additional markers such as irisin, tumor necrosis factor, and interleukin-8 in understanding the multifaceted nature of sarcopenia are acknowledged, their measurements in our study were precluded by logistical constraints and resource limitations." (PMID 38525752, 2024). "Furthermore, sarcopenia is positively correlated with pro-inflammatory cytokines, such as fibrinogen, C-reactive protein, TNF-α, and IL-6, which can promote BC progression." (PMID 39061745, 2024). "For instance, Li’s research indicates that elevated levels of TNF-α (>11.15 pg./mL) are associated with a 7.6-fold increase in the risk of sarcopenia compared to the control group (nonsarcopenia)." (PMID 39588187, 2024). "It has been noted that the release of TNF-α may adversely impact muscle strength and mass as sarcopenia progresses in elderly individuals." (PMID 39588187, 2024). "TNF-α is involved with frailty by promoting inflammation and muscle catabolism or sarcopenia." (PMID 39518709, 2024). "In murine models of sarcopenia, coffee intake increased muscle mass, accelerated the regeneration of injured muscles and decreased some proinflammatory markers such as the interleukins IL-1α, IL-6, and tumor necrosis factor alpha (TNF-α)." (PMID 39275165, 2024). "A meta-analysis published in 2016 indicated that sarcopenia is associated with increased C-reactive protein (CRP) levels but did not confirm the association between sarcopenia and interleukin-6 (IL-6) or tumour necrosis factor α (TNF-α) concentrations." (PMID 38398421, 2024).
sarcopenia (continued). "Notably, cancer-induced hyperuricemia, hyperkaliemia, acute kidney injury (AKI), anorexia, sarcopenia, and high systemic levels of TNF-α, IL-1β, IL-6, and IL-18 can impair heart function, induce myocardial fibrosis and cardiomyocyte atrophy." (PMID 39200115, 2024). "Those pathways associated with muscle wasting, such as extracellular matrix–receptor interaction, protein digestion and absorption; PI3K-Akt signaling, TNF signaling; and NK-kappa B signaling, were strongly enriched in tumors with a higher prevalence of sarcopenia (ESCA, LIHC, and STAD)." (PMID 38397931, 2024). "The relationship between IL6 (interleukin‐6) and sarcopenia in individuals aged more than 65 (P = 0.0001) and the relationship between TNFa (tumour necrosis factor alpha) and sarcopenia in all individuals (P = 0.020) have been reported in a meta‐analysis including 80 studies." (PMID 38556722, 2024). "According to studies in adults, anti-TNF therapy may have a potential positive effect on sarcopenia by inhibiting inflammation and catabolism in skeletal muscles, however the literature is limited." (PMID 36477672, 2023). "TNF-α-stimulated myotube is a well-known in vitro study on sarcopenia." (PMID 36823174, 2023). "Based on previous in vitro studies on sarcopenia, we then used MHC1 as a marker of the in vitro study of sarcopenia to explored whether TNF-α-induced sarcopenia is attributed to GSDME-mediated pyroptosis." (PMID 36823174, 2023). "Indeed, previous studies reported increased levels of IL-6 and TNF, but also higher IL-4 and IL-10, in patients with sarcopenia with respect to healthy individuals." (PMID 38001845, 2023). "Moreover, patients with frailty syndrome and sarcopenia were characterized by a higher serum TNF-α concentration than geriatric patients; however, the difference was not significant." (PMID 37629065, 2023). "Interestingly, sarcopenia alone was not shown to be a risk factor for relapse in the first 12 months after diagnosis, but more children with sarcopenia were treated with anti-TNF drugs, indicating more severe disease." (PMID 37686870, 2023). "However, when serum TNF-α levels were excluded from the multivariate model, our logistic regression analysis revealed that plasma ADMA levels had a stronger association with sarcopenia than TNF-α." (PMID 37015998, 2023). "Most human studies have concentrated on the pro-inflammatory cytokines IL-6 and TNFα contribute to the damaging catabolic effects of inflammation on aging muscle fibers, which leads to skeletal muscle degradation, sarcopenia acceleration, and eventually, a decline in physical performance." (PMID 37465171, 2023). "TNF-α can induce sarcopenia through pyrodeath mediated by Gasdermins." (PMID 37720383, 2023). "In this paper, we established naturally aged mice with sarcopenia model to observe the inflammatory state represented by TNF-α and to identify whether pyroptosis occurs in the skeletal muscle cells." (PMID 36823174, 2023). "However, when the cut-off for sarcopenia was analysed by ANOVA in relation to the continuous variables of the biomarkers, the results showed that sarcopenia correlated significantly with albumin (p < 0.01), Hb (p < 0.01), TNFα (p = 0.02) and CRP (p < 0.01)." (PMID 37906352, 2023). "Our secondary aim was to analyse baseline characteristics of patients with or without risk of sarcopenia at the beginning of anti-TNF therapy and to follow the changes in BC." (PMID 36477672, 2023). "The increase in TNF-α levels is related to lower muscle mass, contributing to sarcopenia." (PMID 36672642, 2023). "In this study, we identified TNF-α and resistin as predictors of sarcopenia in patients with COPD." (PMID 35903456, 2022). "Muscle strength and skeletal muscle mass were significantly correlated with high-sensitivity tumor necrosis factor (TNF), IL-6, and aging, and lower BMI, cardiovascular complications, and elevated high-sensitivity TNF were associated with sarcopenia in COPD patients." (PMID 35611233, 2022).